RNU6-389P (RNA, U6 small nuclear 389, pseudogene)
Gene: Small nuclear RNA gene on chromosome 7 (55,685,977 to 55,686,081, forward strand). Ensembl gene ENSG00000252857.
Homologues: Orthologues: macaque U6 (94% identical), pig U6 (72% identical). Paralogues in human: RNU6-388P (98% identical), RNU6-175P (81% identical), RNU6-1249P (78% identical), RNU6-43P (78% identical), RNU6-727P (78% identical), RNU6-1047P (77% identical), RNU6-115P (77% identical), RNU6-454P (77% identical), RNU6-536P (77% identical), RNU6-668P (77% identical), RNU6-108P (76% identical), RNU6-1091P (76% identical), and 1285 more.